IGKV3-20 (immunoglobulin kappa variable 3-20)
Description:
V region of the variable domain of immunoglobulin light chains that participates in the antigen recognition. Immunoglobulins, also known as antibodies, are membrane-bound or secreted glycoproteins produced by B lymphocytes. In the recognition phase of humoral immunity, the membrane-bound immunoglobulins serve as receptors which, upon binding of a specific antigen, trigger the clonal expansion and differentiation of B lymphocytes into immunoglobulins-secreting plasma cells. Secreted immunoglobulins mediate the effector phase of humoral immunity, which results in the elimination of bound antigens. The antigen binding site is formed by the variable domain of one heavy chain, together with that of its associated light chain. Thus, each immunoglobulin has two antigen binding sites with remarkable affinity for a particular antigen. The variable domains are assembled by a process called V-(D)-J rearrangement and can then be subjected to somatic hypermutations which, after exposure to antigen and selection, allow affinity maturation for a particular antigen.
Synonyms: 13K18; A27; IGKV320
Tractability: Antibody: its Gene Ontology location is reachable by antibodies, with high confidence; UniProt places it where antibodies can reach, with medium confidence; UniProt predicts a signal peptide or a membrane-spanning region; the Human Protein Atlas places it where antibodies can reach. PROTAC: ubiquitination databases record sites on it.
Gene: Immunoglobulin variable (V) gene on chromosome 2 (89,142,574 to 89,143,160, reverse strand). Ensembl gene ENSG00000239951.
Subcellular location: Secreted; Cell membrane
Subcellular location (Human Protein Atlas): Cytosol; Plasma membrane; Predicted to be secreted
Pathways (Reactome):
Immune System: Antigen activates B Cell Receptor (BCR) leading to generation of second messengers; CD22 mediated BCR regulation; Classical antibody-mediated complement activation; FCERI mediated Ca+2 mobilization; FCERI mediated MAPK activation; FCERI mediated NF-kB activation; FCGR activation; Fc epsilon receptor (FCERI) signaling; Immunoregulatory interactions between a Lymphoid and a non-Lymphoid cell; Initial triggering of complement; Regulation of Complement cascade; Regulation of actin dynamics for phagocytic cup formation; Role of LAT2/NTAL/LAB on calcium mobilization; Role of phospholipids in phagocytosis
Disease: FCGR3A-mediated IL10 synthesis; FCGR3A-mediated phagocytosis; Potential therapeutics for SARS
Hemostasis: Cell surface interactions at the vascular wall
Vesicle-mediated transport: Scavenging of heme from plasma
Gene Ontology:
Molecular function: antigen binding
Biological process: antibacterial humoral response; glomerular filtration; immune response
Cellular component: blood microparticle; extracellular exosome; extracellular region; monomeric IgA immunoglobulin complex; pentameric IgM immunoglobulin complex; secretory IgA immunoglobulin complex; immunoglobulin complex; plasma membrane
Homologues: Orthologues: mouse Igkv18-36 (68% identical), rat Igkvl13 (63% identical). Paralogues in human: IGKV3D-20 (97% identical), IGKV3-11 (91% identical), IGKV3OR2-268 (90% identical), IGKV3D-11 (89% identical), IGKV3-15 (87% identical), IGKV3-7 (87% identical), IGKV3D-15 (87% identical), IGKV3D-7 (85% identical), IGKV1D-13 (71% identical), IGKV1-39 (70% identical), IGKV1-5 (70% identical), IGKV1-9 (70% identical), and 81 more.
Diseases named in the same sentence as IGKV3-20 in open-access papers:
IGKV3-20 is named in the same sentence as 11 diseases in open-access papers, as found by Europe PMC text mining. Sharing a sentence is not in itself a finding about the gene and the disease. The quoted sentences say what the papers report.
COVID-19 (2 papers, 2022). A disease caused by infection with severe acute respiratory syndrome coronavirus 2. "Specifically, within upregulated, CAZA1, CO4A, ANXA4, and immunoglobulin kappa variable 3–20 (IGKV3-20) were significantly increased in mild disease COVID-19 while ACTN4 and fibrinogen beta (FGB) chain were significantly increased in severe COVID-19 individuals." (PMID 35760827, 2022).
autoimmune disease (1 paper, 2014). A disorder resulting from loss of function or tissue destruction of an organ or multiple organs, arising from humoral or cellular immune responses of the individual to their own tissue constituents. "Unexpectedly, CD274 molecule, which has been speculated to play a major role in suppressing the immune system during autoimmune disease and disease states, including hepatitis, is down-regulated by IGKV3-20 in PBMCs of MML while strongly up-regulated in all the other HCV-positive samples." (PMID 24428943, 2014).
gastric lymphoma (1 paper, 2016). An extranodal lymphoma that arises from the stomach with the bulk of the mass located in the stomach. "28S rRNA has been identified as a novel fusion partner of carcinoma-related genes such as BCL6, BCL11B, IGKV3-20, and COG1 in gastric lymphoma or hematopoietic tumors." (PMID 27517048, 2016).
tumor (2 papers, 2022 to 2025). "The MFP proteome was enriched for several immune-related and plasma proteins more indicative of inflammatory infiltration and chronic immune activation rather than tumor-specific remodeling including C1QB, CFH, MZB1, IGKV3-20, ORM2, ALB, and AZGP1." (PMID 41007761, 2025).
IGKV3-20 also shares sentences with these, for which no sentence is quoted: viral infection (3 papers); cancer (2); infection (2); abdominal aortic aneurysm (1); arteritis (1); atherosclerosis (1); Hepatitis (1).